RAB12 (RAB12, member RAS oncogene family)
Description:
The small GTPases Rab are key regulators of intracellular membrane trafficking, from the formation of transport vesicles to their fusion with membranes. Rabs cycle between an inactive GDP-bound form and an active GTP-bound form that is able to recruit to membranes different sets of downstream effectors directly responsible for vesicle formation, movement, tethering and fusion (By similarity). RAB12 may play a role in protein transport from recycling endosomes to lysosomes regulating, for instance, the degradation of the transferrin receptor. Involved in autophagy (By similarity).
Gene: Protein-coding gene on chromosome 18 (8,609,437 to 8,639,383, forward strand). Ensembl gene ENSG00000206418.
Subcellular location: Recycling endosome membrane; Lysosome membrane; Golgi apparatus membrane; Cytoplasmic vesicle, autophagosome
Subcellular location (Human Protein Atlas): Vesicles
Pathways (Reactome):
Metabolism of proteins: RAB geranylgeranylation
Vesicle-mediated transport: RAB GEFs exchange GTP for GDP on RABs
Genetic constraint (gnomAD): Loss-of-function variants: 7 observed, 11.14 expected, observed/expected ratio (o/e) 0.63, 90% interval 0.36 to 1.18. The upper end of that interval is the gene's LOEUF score, 1.18, which puts it in group 5 of 6, group 1 being the genes least tolerant of losing a copy. Missense variants: 126 observed, 172.95 expected, observed/expected ratio (o/e) 0.73, 90% interval 0.63 to 0.85. Synonymous variants: 88 observed, 71.26 expected, observed/expected ratio (o/e) 1.24, 90% interval 1.04 to 1.47.
Homologues: Orthologues: macaque RAB12 (96% identical), dog RAB12 (94% identical), pig RAB12 (91% identical), mouse Rab12 (79% identical), rat Rab12 (79% identical), chimpanzee RAB12 (72% identical), tropical clawed frog rab12 (64% identical), guinea pig RAB12 (60% identical), zebrafish rab12 (59% identical), rabbit RAB12 (54% identical). Paralogues in human: RAB10 (29% identical), RAB1A (29% identical), RAB1B (29% identical), RAB13 (28% identical), RAB8B (28% identical), RAB8A (27% identical), RAB3C (26% identical), RAB3A (26% identical), RAB3B (26% identical), RAB35 (26% identical), RAB3D (25% identical), RAB18 (25% identical), and 56 more.
Diseases named in the same sentence as RAB12 in open-access papers:
RAB12 is named in the same sentence as 36 diseases in open-access papers, as found by Europe PMC text mining. Sharing a sentence is not in itself a finding about the gene and the disease. The quoted sentences say what the papers report.
Parkinson disease (9 papers, 2017 to 2025). A progressive degenerative disorder of the central nervous system characterized by loss of dopamine producing neurons in the substantia nigra and the presence of Lewy bodies in the substantia nigra and locus coeruleus. "Overall, these results highlight a new, Rab12-dependent mechanism that results in enhanced activity at the lysosomal membrane with variants associated with Parkinson’s disease, and for LRRK2 in general when lysosomes are damaged." (PMID 37874617, 2023). "Next, we tested 916 additional dystonia patients; 512 Parkinson’s disease patients; and 461 healthy controls for RAB12 variants and identified 10 additional carriers of rare missense changes among dystonia patients (1.1%) but only one carrier in non-dystonic individuals (0.1%; p = 0.005)." (PMID 29057844, 2017). "The most common cause of familial Parkinson’s disease is linked to mutations in the leucine rich-repeat kinase 2 (LRRK2) protein that phosphorylates Rab10, Rab8a, Rab12 and Rab35." (PMID 40801573, 2025). "Future studies addressing these questions will help clarify the broader physiological and pathological significance of Rab12 phosphorylation and its effector interactions in allergy, neurogenic inflammation, and Parkinson’s disease." (PMID 41357239, 2025). "Rab12 regulates LRRK2 activation basally and in response to lysosomal damage and genetic variants associated with Parkinson’s disease (PD)." (PMID 37874617, 2023). "Our findings of increased Rab12 phosphorylation and pS106-Rab12 labeling of GVBs and pathology across synucleinopathies and tauopathies suggest that LRRK2 plays a role in other neurodegenerative diseases in addition to Parkinsonism." (PMID 40661559, 2025). "In mouse melanocytes, which express high levels of Rab38, Rab32, and Rab29, knockdown (or CRISPR knockout) of Rab38, but not Rab32 or Rab29, decreases phosphorylation of multiple LRRK2 substrates, including Rab10 and Rab12, by both endogenous LRRK2 and exogenous Parkinson’s disease-mutant LRRK2." (PMID 37625589, 2023).
cervical cancer (3 papers, 2021 to 2024). A primary or metastatic malignant neoplasm involving the cervix. "have reported that the Ras-associated binding protein Rab12 mRNA and protein expressions are upregulated in cervical cancer tissues, and that Rab12 promotes radioresistance by inducing a G2/M arrest." (PMID 37023702, 2023). "In this study, we explored the mechanism by which Rab12 promotes radioresistance of cervical cancer cells." (PMID 33718142, 2021). "Association of clinicopathological characteristics of patients with cervical cancer and Rab12 expression." (PMID 33718142, 2021). "Studying the role of Rab12 in cervical cancer radiotherapy provide new targets for improving the therapeutic effectiveness of HPV-positive cervical cancers." (PMID 33718142, 2021). "Rab12 mRNA and protein expressions were up-regulated in cervical cancer tissues and HPV+ cervical cancer cells." (PMID 33718142, 2021). "Our previous mass spectrometry data showed that Ras-associated binding protein Rab12 was up-regulated by HPV, and this study is to investigate the role of Rab12 in the radioresistance of HPV-positive cervical cancer cells." (PMID 33718142, 2021). "Our study reveals a molecular mechanism of radioresistance mediated by Rab12 in HPV-positive cervical cancer and helps to identify potential therapeutic targets to improve the efficiency of clinical treatment of cervical cancer." (PMID 33718142, 2021). "Compared with other cervical cancer cell lines, the expression level of Rab12 was the highest in SiHa cells; thus, we used a lentivirus to knock down Rab12 expression in SiHa cells to study its effect on the radiosensitivity of cervical cancer cells." (PMID 33718142, 2021). "Additionally, we showed that radiation promoted the expression of Rab12, thus we further explored the role of Rab12 in radioresistance of HPV-positive cervical cancer cells." (PMID 33718142, 2021). "To test whether Rab12 affected the radiosensitivity of cervical cancer cells, we used lentivirus shRab12 to infect SiHa cells to knock down Rab12 expression." (PMID 33718142, 2021). "Rab12 protein was highly expressed in cervical cancer cells." (PMID 33718142, 2021). "Our results showed that cells with Rab12 knockdown formed fewer cell colonies, and both the survival fraction and the cell viability were lower compared with the control cells after radiation, indicating that Rab12 knockdown increased the radiosensitivity of cervical cancer cells." (PMID 33718142, 2021). "In short, radiation promoted the expression of Rab12 in HPV+ cervical cancer cells." (PMID 33718142, 2021). "We first detected Rab12 mRNA expression in cervical cancer tissues." (PMID 33718142, 2021). "In this study, we explored the mechanism of Rab12 in radioresistance of cervical cancer cells." (PMID 33718142, 2021). "Rab12 may serve as a potential therapeutic target to improve clinical treatment outcome of cervical cancer." (PMID 33718142, 2021). "To investigate whether Rab12 could be an independent prognostic factor with cervical cancer, we performed survival analysis with overall survival (OS)." (PMID 33718142, 2021). "In addition, we measured Rab12 protein levels in several cervical cancer cell lines using human immortal keratinocytes HaCat cells as a negative control." (PMID 33718142, 2021). "Next, we investigated whether Rab12 regulated apoptosis of cervical cancer cells after radiation." (PMID 33718142, 2021). "Thus, Rab12 enhanced the radioresistance of cervical cancer cells." (PMID 33718142, 2021). "The expression of Rab12 has been demonstrated to be significantly upregulated in both cervical cancer tissues and HPV-positive cervical cancer cell lines." (PMID 38651153, 2024). "Since the expression of Rab12 was the highest in HPV+ SiHa cells and squamous carcinoma accounts for 80% of cervical cancers, we focused on SiHa cells for further study." (PMID 33718142, 2021).
cervical cancer (continued). "Our results demonstrated that HPV oncoproteins E6 and E7 up-regulated Rab12 expression, and the expression of Rab12 in HPV-positive cervical cancer cells was higher than in HPV-negative C33A cells." (PMID 33718142, 2021). "In conclusion, our results demonstrate that Rab12 is highly expressed in cervical cancer tissues and HPV+ cervical cancer cell lines." (PMID 33718142, 2021). "Our previous mass spectrometry data showed that Rab12 was up-regulated by HPV (data not shown), but the role of Rab12 in cervical cancer is still unclear." (PMID 33718142, 2021). "The results showed that cells with Rab12 knockdown formed less cell colonies, and the survival fraction and the cell viability were lower compared with control cells after radiation, indicating that knockdown of Rab12 increased the radiosensitivity of HPV+ cervical cancer cells." (PMID 33718142, 2021). "However, there has been no report of a direct relation between Rab12 and cervical cancer." (PMID 33718142, 2021).
colorectal cancer (2 papers, 2020 to 2021). A primary or metastatic malignant neoplasm that affects the colon or rectum. "The combination of gene expression analysis and CNA analysis showed that Rab12 was significantly highly expressed in colorectal cancer with lymph node metastasis, suggesting that Rab12 could be a potential oncogene involved in colorectal cancer." (PMID 33718142, 2021).
basophilic leukemia (1 paper, 2017). "This idea is supported by recently published findings showing perinuclear clustering of constitutively active RAB12 in RBL-2H3 (rat basophilic leukemia) cells." (PMID 29057844, 2017).
choroideremia (1 paper, 2024). Choroideremia (CHM) is an X-linked chorioretinal dystrophy characterized by progressive degeneration of the choroid, retinal pigment epithelium (RPE) and retina. "This study supports Rab12 under-prenylation as an important cause of RPE cell dysfunction in choroideremia and highlights increased mTORC1 and reduced autophagy as potential disease pathways for further investigation." (PMID 38920696, 2024). "They found that Rab12 was the least prenylated by far in CHM-/y cells, at 10% of wild-type levels, consistent with our findings in human CHM−/− iPSC-RPE cells that Rab12 is the least prenylated and further supporting the role of Rab12 in choroideremia." (PMID 38920696, 2024). "RPE autophagy, or upstream mTORC1 signaling or Rab12 prenylation, may therefore warrant further investigation as a promising future therapeutic target to save vision in choroideremia." (PMID 38920696, 2024). "In summary, this study defines the spectrum of unprenylated Rabs in the tissue of interest in choroideremia using a human RPE model and further demonstrates downstream consequences of unprenylated Rab12, one of the most severely unprenylated Rabs in our study." (PMID 38920696, 2024). "Furthermore, partial knockdown of Rab12 in control iPSC-RPE cells reproduced the increased mTORC1 signaling and reduced the autophagy phenotype seen with CHM knockout, further supporting the importance of Rab12 in RPE autophagic dysfunction in choroideremia." (PMID 38920696, 2024).
colitis (1 paper, 2025). Inflammation of the colon. "In summary, we found that deletion of Rab12 significantly reduces N2081D-associated colitis severity, highlighting its potential as a therapeutic target." (PMID 41031878, 2025). "We next examined the impact of RAB12 loss on symptoms of induced colitis in Lrrk2N2081D mice." (PMID 41031878, 2025). "In contrast, our study showed that Rab12 deletion significantly reduced phosphorylated RAB10 levels in colon tissue and led to a marked improvement in colitis severity across multiple readouts." (PMID 41031878, 2025). "Rab12 KO reduces RAB10 phosphorylation and alleviates colitis severity in Lrrk2N2081D mice." (PMID 41031878, 2025). "Finally, we show that knockout of Rab12, but not pharmacological LRRK2 kinase inhibition, significantly reduced colitis severity in Lrrk2N2081D mice." (PMID 41031878, 2025).
cyst (1 paper, 2015). A sac-like closed membranous structure that may be empty or contain fluid or amorphous material. "A total of 6 specific proteins in the resting cyst were found in our study, which included fibrillarin-like rRNA methylase, methylmalonyl-coenzyme A mutase, ADP ribosylation factor, Rab12, MAPK-related kinase and KR multi-domain protein." (PMID 26079518, 2015).
Dystonia (1 paper, 2017). An abnormally increased muscular tone that causes fixed abnormal postures. "Taken together, we provide first insights into a possibly pathological function of mutated RAB12 in MD and other forms of dystonia." (PMID 29057844, 2017). "Despite RAB12’s important role and plausible link between its function and a neurological disease, screening of additional patient cohorts is warranted to confirm the pathogenicity of RAB12 mutations in dystonia patients." (PMID 29057844, 2017). "Functional characterization revealed altered enzyme activity and lysosomal distribution in mutants suggesting a contribution of RAB12 variants to MD and other dystonias." (PMID 29057844, 2017). "Recent exome sequencing of Families A, B, and D with good coverage (mean coverage depth: 120×, with approximately 95% of bases covered at >20×) excluded known dystonia genes and confirmed RAB12 as the only plausible candidate." (PMID 29057844, 2017). "Additional RAB12 variants were found in other dystonia patients but were largely absent in the investigated controls as well as in publically available databases." (PMID 29057844, 2017).
gastric cancer (1 paper, 2021). A primary or metastatic malignant neoplasm involving the stomach. "Rab12 mRNA levels was significantly up-regulated in cisplatin-resistant gastric cancer cells compared with cisplatin-sensitive cells." (PMID 33718142, 2021).
Hirschsprung disease (1 paper, 2021). Hirschsprung disease (HSCR) is a congenital intestinal motility disorder that is characterized by signs of intestinal obstruction due to the presence of an aganglionic segment of variable extent in the terminal part of the colon. "In the context of pathology, among the genes recently associated with Hirschsprung disease (HSCR), showing impaired enteric nervous system development, WES analysis identified mutations affecting the GEF DENND3, typically involved in intracellular trafficking by activation of RAB12." (PMID 34124035, 2021).
lymph node metastasis (1 paper, 2021). "However, Rab12 expression was not correlated with age, differentiation status, tumor size, lymph node metastasis, direct metastasis, vascular invasion, histological grade, or clinical stage." (PMID 33718142, 2021).
synucleinopathies (1 paper, 2025). "In summary, we found increased Rab12 phosphorylation and localization of pS106-Rab12 to tau and α-synuclein pathology in tauopathies and synucleinopathies, including LRRK2 PD, iPD, DLB, AD and primary tauopathies." (PMID 40661559, 2025). "We found that LRRK2 is activated in neurodegenerative diseases and associated with tau pathology, evidenced by elevated Rab12 phosphorylation in DLB subjects with high tau pathology and labeling of GVBs as well as mature tau and α-synuclein pathology in tauopathies and synucleinopathies." (PMID 40661559, 2025). "In addition to labeling of these lysosomal GVBs, phosphorylated Rab12 was increased in the hippocampus and temporal cortex and labeled a subset of mature pathological tau and α-synuclein inclusions in human tauopathies and synucleinopathies." (PMID 40661559, 2025).
cancer (5 papers, 2015 to 2023). A tumor composed of atypical neoplastic, often pleomorphic cells that invade other tissues. "Rab12 mRNA levels were significantly elevated in cancer tissues (p<0.01) compared to non-cancer cervix tissues." (PMID 33718142, 2021). "Another recent study showed that RAB12 member RAS oncogene family (RAB12) is an endogenous mTORC1 inhibitory factor and protects cancer cells from drug-induced cell death by activating cytoprotective autophagy." (PMID 31861937, 2019). "RAB12 is targeted by miR-148-3p; therefore, the introduction of miR-148-3p in cancer cells can reverse therapeutic resistance." (PMID 31861937, 2019). "However, in this study, we showed that the Rab12-induced radioresistance of cancer cells was not related to apoptosis." (PMID 33718142, 2021).
neurodegenerative disease (1 paper, 2025). A disorder of the central nervous system characterized by gradual and progressive loss of neural tissue and neurologic function. "We sought to determine whether Rab12 phosphorylation mediated by LRRK2 is altered in neurodegenerative diseases with tau and/or α-synuclein pathology." (PMID 40661559, 2025). "In this study, we tested whether aberrant LRRK2 activity is associated with tau and/or α-synuclein pathology in clinically distinct neurodegenerative diseases by analyzing LRRK2-mediated phosphorylation of Rab12 at amino acid Ser106 (pS106-Rab12)." (PMID 40661559, 2025). "Considering both pathological α-synuclein and tau accumulation induce endolysosomal stress, and both proteins can be degraded by lysosomes, LRRK2 and Rab12 may play fundamental roles in mediating early stages of α-synuclein and tau pathology in neurodegenerative diseases." (PMID 40661559, 2025). "We observed elevated Rab12 phosphorylation in hippocampus and entorhinal cortex of DLB cases, as well as increased pS106-Rab12 labeling across neurodegenerative diseases with tau and/or α-synuclein pathology." (PMID 40661559, 2025).
RAB12 also shares sentences with these, for which no sentence is quoted: lung carcinoma (2 papers); tumor (2); Allergy (1); Alzheimer disease (1); amyloid (1); Autoimmunity (1); breast carcinoma (1); colon cancer (1); corticobasal degeneration (1); Dementia with Lewy bodies (1); head and neck squamous cell carcinoma (1); infection (1); Neurofibrillary tangles (1); neurological disease (1); osteosarcoma (1); Parkinsonism (1); Pick disease (1); progressive supranuclear palsy (1); schizophrenia (1); squamous carcinoma (1); tauopathies (1); thyroid disease (1).